MAPT (microtubule associated protein tau)
Diseases named in the same sentence as MAPT in open-access papers (continued):
Sharing a sentence is not in itself a finding about the gene and the disease.
tauopathies (continued). "Tauopathy, the pathological accumulation and spread of misfolded aggregates of microtubule-associated protein tau, is among the most common types of proteinopathies implicated in neurodegenerative disease, including AD, FTLD, Pick’s disease, and others." (PMID 34314441, 2021). "Specifically, we used iPSC-derived neurons from a tauopathy patient with a MAPT missense mutation encoding A152T." (PMID 34426604, 2021). "Brain samples from frontotemporal lobar degeneration due to microtubule associated protein tau (FTLD-MAPT) mutations were also included as a distinct tauopathy phenotype for comparison." (PMID 34172091, 2021). "Protein synthesis is impaired in neurodegenerative diseases including tauopathies, in which pathology is caused by aberrant changes to the microtubule-associated protein tau." (PMID 34147135, 2021). "As such, the histopathological findings can vary widely between 3 and 4R tauopathies, and between sporadic and inherited tauopathies secondary to MAPT mutations." (PMID 34389969, 2021). "It is only when the MAPT gene was expressed with a tauopathy-associated mutation, increasing the quantity of the four-repeat tau isoform, that the first observations of tau hyperphosphorylation and pretangle formation were reported in mice." (PMID 34445475, 2021). "From a genetic point of view, hereditary tauopathies are characterized by the presence of a variant in the MAPT gene encoding the Tau protein or inheritance of the H1 haplotype of the MAPT locus." (PMID 33924882, 2021). "The microtubule-associated protein tau (tau) forms hyperphosphorylated aggregates in the brains of tauopathy patients that can be pathologically and biochemically defined as distinct tau strains." (PMID 33385254, 2021). "There are also different MAPT haplotypes, of which H1 has been associated with an elevated risk of developing a number of primary tauopathies relative to those bearing the H2 haplotype." (PMID 34200180, 2021). "The term “tauopathy” was first used for a condition with a mutation in the tau (MAPT) gene, which seems appropriate since tau protein itself is mutated in this condition and associated with autosomal dominant disease." (PMID 33322544, 2020). "Determining the precise nature of the relationship between genetic variation and the expression of MAPT region genes will undoubtedly provide additional insights into tauopathy and thus LOAD risk." (PMID 32265636, 2020). "Of note, genome-wide association studies have shown that genetic variants of MAPT mutations were associated with both tauopathies and synucleinopathies, while SNCA mutations were associated with NFTs’ pathology." (PMID 32708732, 2020). "Tauopathies are neurodegenerative disorders characterized by the deposition of abnormal microtubule-associated protein tau (MAPT) in the brain." (PMID 33203009, 2020). "The microtubule associated protein tau interacts with α-syn and there is a substantial overlap of tauopathies with synucleinopathies." (PMID 33262984, 2020). "In tauopathies including Alzheimer’s disease and frontotemporal lobar dementia with MAPT mutations, regional changes in cerebral blood flow have been observed, implicating vascular dysfunction as a common feature of diseases that include tau accumulation." (PMID 32811565, 2020). "The P301S mouse model, which expresses the mutant human microtubule-associated protein tau was developed to study mechanisms of tauopathy." (PMID 32751531, 2020). "Tauopathies are a group of diseases that are all characterized by neuropathological phosphorylation and aggregation of the microtubule associated protein tau (MAPT)." (PMID 32982685, 2020). "In this case series, we report 2 individuals who presented with FTD and were found to have novel pathogenic MAPT mutations with subsequent pathological confirmation of a primary tauopathy." (PMID 31870644, 2020). "Subtypes of MAPT mutations were associated with different AV-1451 uptake patterns due to different types of underlying tauopathies." (PMID 32184751, 2020).
tauopathies (continued). "Our results also indicate that, within the genetic and pathological diagnoses, the basal forebrain is mainly involved in individuals with tauopathies, specifically those with MAPT mutations (FTDP-17), and also those with Pick's disease pathologically." (PMID 32143137, 2020). "In FTDP-17, an inherited tauopathy, single nucleotide polymorphisms [SNP, ≥47] are present on the MAPT gene are causally related to a wide variety of clinical symptoms." (PMID 33343298, 2020). "Familial tauopathies with MAPT mutations are often classified as FTDP-17 (familial frontotemporal dementia with Parkinsonism linked to chromosome-17)." (PMID 33121065, 2020). "In tauopathies, the microtubule associated protein tau becomes hyperphosphorylated (as phospho-tau) and aggregates within neurons and glia." (PMID 32327969, 2020). "Tauopathies are neurodegenerative diseases characterized by the pathological accumulation of microtubule-associated protein tau (MAPT) in the form of neurofibrillary tangles and paired helical filaments in neurons and glia, leading to brain cell death." (PMID 33255694, 2020). "The results of our current study add to the understanding of the genetic etiology of this rare tauopathy by shedding further light on the strongest genetic risk factor for CBD that has been observed thus far—the MAPT H1 haplotype." (PMID 33287913, 2020). "While many MAPT mutations increase tau’s propensity for aggregation and toxicity, and are the cause of dominantly inherited tauopathies, the majority of tauopathies are sporadic with variable clinical and pathological presentations." (PMID 33255694, 2020). "Tau transgenic mice overexpress the human MAPT gene with disease-causing mutations (often P301S or P301L) and are often used to model tauopathy associated with AD." (PMID 32733196, 2020). "Impaired alternative splicing of exon 10 of the MAPT gene leads to an imbalance in the amount of 3R and 4R tau isoforms within cells, and a change in 3R to 4R ratio has been associated with specific tauopathies." (PMID 33329322, 2020). "Missense, silent and intronic mutations in the MAPT gene have been directly related to different Tauopathies or constitute a risk factor for them." (PMID 32009905, 2019). "Tauopathies represent a heterogeneous group of neurodegenerative disorders characterized by abnormal deposition of the hyperphosphorylated microtubule-associated protein tau." (PMID 31120951, 2019). "Tauopathies are clinically, biochemically and morphologically heterogeneous neurodegenerative diseases characterized by the deposition of abnormal tau (microtubule associated protein tau; MAPT) in the brain." (PMID 30767766, 2019). "The MAPT A152T rare variant is considered a risk factor for tauopathies including FTLD-tau and AD, and we included both of the patients with this variant available within the UCSF Neurodegenerative Disease Brain Bank." (PMID 31640778, 2019). "Tauopathies are a group of disorders characterized by the abnormal accumulation of the microtubule-associated protein Tau." (PMID 31118883, 2019). "Little is known about factors that modify age at onset in the MAPT group, although a recent study suggested that ApoE ε4 carriers had a lower age at onset in tauopathies including MAPT mutations." (PMID 31119452, 2019). "Tauopathies can be either sporadic or inherited as autosomal dominant disease when caused by mutations in the MAPT gene encoding the microtubule-associated protein tau." (PMID 30907729, 2019). "The microtubule-associated protein tau gene (MAPT) rs242557 variant is associated with multiple tauopathies and dementia." (PMID 30708351, 2019). "Tauopathies are a class of neurodegenerative disorders characterized by the formation of neurofibrillary tangles and paired helical filaments composed of microtubule-associated protein tau (MAPT)." (PMID 31434312, 2019).
tauopathies (continued). "Tauopathies associated with MAPT mutations include familial and sporadic frontotemporal dementia (FTD) (also referred to as “frontotemporal lobar degeneration with MAPT mutation (FTLD-tau)”)." (PMID 30373150, 2018). "The FTDP-17 subtype associated with the MAPT mutation pathologically exhibits extensive tauopathy, while TDP-43–positive abnormal inclusions are the pathological hallmark in FTDP-17 associated with GRN mutations." (PMID 30518093, 2018). "Tauopathies are a group of dementias that have in common the formation of intracellular filamentous deposits seeded by the microtubule-associated protein tau, in abnormally hyperphosphorylated form(s)." (PMID 30356756, 2018). "The aberrant activation of tau kinases and MAPT mutations appear the most causative reasons for tau dysregulation in tauopathies." (PMID 30174587, 2018). "Tauopathies are neurodegenerative disorders characterized by microtubule-associated protein tau (MAPT) hyperphosphorylation and aggregation into paired helical filaments (PHFs) or straight filaments (SFs), forming neurofibrillary tangles (NFTs) in brain." (PMID 30619849, 2018). "Transgenic mice harboring these MAPT mutations are widely employed as in vivo models for tauopathies." (PMID 30425303, 2018). "Although the majority of tauopathies occur sporadically, more than 50 pathogenic MAPT mutations were identified in approximately 150 families with tauopathies." (PMID 30373150, 2018). "One main group of NDDs is associated with abnormal accumulation of the microtubule-associated protein tau, hence called tauopathies." (PMID 29891013, 2018). "The H1 haplotype of the MAPT gene is associated with a risk of PD, as well as in sporadic tauopathies." (PMID 30373150, 2018). "Tauopathies represent heterogeneous groups of neurodegenerative diseases that are characterised by abnormal deposition of the microtubule-associated protein tau." (PMID 28934963, 2017). "MAPT has been implicated in a suite of so-called tauopathies characterized by progressive neurological deficit, and is also a risk locus for Parkinson’s disease." (PMID 29313844, 2017). "Although mutations in the Tau-encoding MAPT gene underlie a set of neurodegenerative disorders, termed tauopathies, the exact contribution of MT dynamics and the perturbation thereof to neuronal network connectivity has not yet been scrutinized." (PMID 28690500, 2017). "Microtubule associated protein tau (tau) deposition is associated with a spectrum of neurodegenerative diseases collectively termed tauopathies." (PMID 28077166, 2017). "While primary Tauopathies include corticobasal degeneration and progressive supranuclear palsy, cases with germline mutations in the Tau gene (MAPT) are also notable." (PMID 28978354, 2017). "Tauopathies are a group of neurodegenerative diseases showing characteristic deposits of the microtubule-associated protein tau in the form of intracellular neurofibrillary tangles in the central nervous system." (PMID 28233851, 2017). "In spite of these challenges, numerous reports now describe successful modelling of tauopathy in iPSC-neurons with MAPT mutations." (PMID 28610595, 2017). "The term Tauopathy was used for the first time to define the family with the +3 MAPT mutation (see also the article “What is the evidence that the spread of tau pathology occurs via a prion-like mechanism?” in this issue)." (PMID 29187252, 2017). "In tauopathies such as frontotemporal dementia and Alzheimer's disease (AD), mutations are frequently found in MAPT, the gene encoding Tau." (PMID 28690500, 2017). "Senile plaque is an extracellular accumulation of Aβ which is composed of soluble oligomer Aβ, while NFTs are intraneuronal aggregates of the highly phosphorylated microtubule-associated protein tau, also referred to as tauopathy." (PMID 28790888, 2017).
tauopathies (continued). "Tauopathies constitute a group of neurodegenerative disorders associated with molecular alterations in the microtubule associated protein tau that can be sub-classified by the predominant species of tau that accumulates within neurons and glia." (PMID 27296779, 2016). "Structural and biochemical alterations of the microtubule-associated protein tau (MAPT) are associated with degenerative disorders referred to as tauopathies." (PMID 26824039, 2016). "Tauopathies are characterized by progressive cognitive and/or motor dysfunction, together with highly phosphorylated aggregates of the microtubule-associated protein tau in brain and peripheral nerve." (PMID 27297240, 2016). "Neurofibrillary tangle (NFT) pathology, one of the major pathological hallmarks of AD and related tauopathies, occurs when microtubule-associated protein tau (MAPT or tau) undergoes hyperphosphorylation and aggregates as NFTs." (PMID 27974048, 2016). "We find that several genes associated with tauopathies, such as the MAPT gene (involved in production of τ proteins), are expressed in many tissues, indicating that gene expression alone is a poor predictor of the tissue-specificity of the disease." (PMID 27748412, 2016). "A certain number of mutations in the Microtubule-Associated Protein Tau (MAPT) gene have been identified in individuals with high risk to develop neurodegenerative diseases, collectively called tauopathies." (PMID 27118310, 2016). "MAPT H1/H1 genotype has been firmly established not only as a risk factor for tauopathies, including progressive supranuclear palsy (PSP) and corticobasal degeneration (CBD), but also associated with increased PD risk." (PMID 27242557, 2016). "Two common haplotypes exist at the MAPT locus, H1 and H2, and H1 is associated with increased risk of the 4R tauopathies PSP and CBD." (PMID 26136155, 2015). "In tauopathies, a neural microtubule-associated protein tau (MAPT) is abnormally aggregated and forms neurofibrillary tangle." (PMID 25659102, 2015). "The relationship between Tau proteins and pathophysiology is supported by the identification of autosomal dominant mutations in the Tau gene, MAPT, in various tauopathies, such as frontotemporal dementia with parkinsonism linked to chromosome 17 (FTDP-17)." (PMID 26170022, 2015). "Our demonstration that MAPT mutations cause common and specific phenotypes will improve the understanding of disease mechanisms prompting the search for new therapies for tauopathies." (PMID 26220942, 2015). "Although it is not fully understood how the increase in 4R-tau contributes to disease pathogenesis, MAPT mutations have been shown to cause multiple tauopathies." (PMID 26373282, 2015). "MAPT is implicated in progressive supranuclear palsy, in part because of the discovery of splicing mutations in another 4R-tauopathy, frontotemporal dementia with parkinsonism linked to chromosome 17 (FTDP-17)." (PMID 25061481, 2014). "Tauopathies are a heterogeneous group of neurodegenerative diseases with the common feature of intracellular aggregation of the microtubule associated protein tau." (PMID 25402454, 2014). "Both common and rare genetic variation in MAPT have been strongly implicated in primary tauopathies." (PMID 25324900, 2014). "Despite having tauopathy as a defining lesion, reports of association between AD and genetic variants at the MAPT locus are inconsistent." (PMID 25324900, 2014). "The MAPT H1 haplotype is therefore considered a genetic risk factor for a myriad of neurodegenerative disorders, including both pure tauopathies (PSP and CBD) and synucleinopathies (PD, PDD and MSA)." (PMID 25352339, 2014). "Monogenetic MAPT mutations are responsible for some hereditary tauopathies, where so far, 51 disease-causing MAPT mutations are known." (PMID 25437199, 2014). "Abundant and abnormal accumulation of the hyperphosphorylated microtubule-associated protein Tau is a pathological feature of the neurodegenerative diseases known as tauopathies." (PMID 24971751, 2014).
tauopathies (continued). "Mutations in the MAPT gene that encodes the tau protein are known to cause some of these tauopathies, including variants of frontotemporal dementia and progressive supranuclear palsy." (PMID 25183004, 2014). "Accumulation of microtubule-associated protein tau has been observed in the brain of aging and tauopathies." (PMID 24146816, 2013). "Microtubule-associated protein tau (MAPT) mutations have been shown to underlie frontotemporal dementia and a variety of additional sporadic tauopathies." (PMID 22595371, 2012). "Surprisingly, we observe hyperphosphorylation and filament formation of the microtubule-associated protein tau, reminiscent of a large group of neurodegenerative disorders termed tauopathies." (PMID 23144624, 2012). "Other researchers have developed models of human tauopathies based on transgenes expressing disease causing variants of the microtubule-associated protein tau." (PMID 21912750, 2011). "Tauopathies are a group of neurodegenerative diseases characterised by abnormally hyperphosphorylated and insoluble aggregates of the microtubule-associated protein tau." (PMID 22254145, 2011). "Pathological aggregation of the microtubule-associated protein tau is a defining feature not only of AD but also of other neurodegenerative diseases collectively called tauopathies." (PMID 20522007, 2010). "Abnormalities of microtubule-associated protein tau play a central role in neurofibrillary degeneration in several neurodegenerative disorders that collectively called tauopathies." (PMID 18616804, 2008). "The H1 haplotype of MAPT has been found to be closely associated with tauopathies and with sporadic FTLD." (PMID 19091059, 2008). "MAPT‐FTD is a rare form of FTD linked to mutations in the MAPT gene and presents with distinct clinical manifestations, including changes in behavior, motor function, memory, and/or language, and is less common than other tauopathies." (PMID 40437880, 2025). "In addition, over 60 genetic mutations in the MAPT gene locus have been linked to tauopathies as either disease-causing or risk factors." (PMID 40082954, 2025). "While both are defining features of AD, NFTs are characterized by abnormal accumulation of the microtubule-associated protein tau (MAPT), and a group of neurodegenerative diseases characterized by tau aggregation and dysfunction are collectively known as “tauopathies”." (PMID 41008617, 2025). "Moreover, transgenic zebrafish expressing human MAPT (microtubule-associated protein tau) have been developed to visualize tauopathy-related processes in vivo." (PMID 41302176, 2025). "Overall, our data indicates that the MAPT P301S mutation and accumulation of pTau are associated with distinct brain lipidomes in vivo, further implicating altered lipid metabolism as a potential pathogenic and druggable process in primary tauopathies." (PMID 41318029, 2025). "Tauopathies represent a heterogeneous group of approximately 20 different neurodegenerative diseases characterized by the abnormal deposition of the microtubule-associated protein tau (MAPT) in cells of the nervous system." (PMID 40331982, 2025). "Similarly, in FTD, key proteins implicated in tauopathies and neurofilament dynamics were identified: MAPT (β = −0.32, P = 3.1 × 10−5) and NEFL (β = 0.28, P = 2.3 × 10−4)." (PMID 40665052, 2025). "MAPT gene mutations may lead to tauopathies, in which tau becomes hyperphosphorylated and begins to form neurofibrillary tangles (NFTs), which play an important role in the neurodegenerative process." (PMID 40722695, 2025). "Hyperphosphorylation and aggregation of microtubule-associated tau (MAPT/Tau) is one of the hallmark pathologies of AD and a defining feature of a group of neuronal disorders termed tauopathies, including progressive supranuclear palsy, corticobasal degeneration, and frontotemporal dementias (FTDs)." (PMID 40395993, 2025). "Over 80 MAPT mutations have been discovered to be associated with tauopathies." (PMID 40588759, 2025).